RNU1-131P (RNA, U1 small nuclear 131, pseudogene)
Gene: Small nuclear RNA gene on chromosome 20 (17,209,060 to 17,209,220, forward strand). Ensembl gene ENSG00000238833.
Homologues: Orthologues: chimpanzee U1 (99% identical), macaque U1 (94% identical), pig U1 (81% identical). Paralogues in human: RNU1-1 (86% identical), RNU1-2 (86% identical), RNU1-27P (86% identical), RNU1-28P (86% identical), RNU1-3 (86% identical), RNU1-4 (86% identical), RNVU1-18 (86% identical), RNVU1-29 (86% identical), U1 (86% identical), RNU1-89P (86% identical), RNVU1-28 (86% identical), RNVU1-7 (86% identical), and 133 more.